CYP2E1 (cytochrome P450 family 2 subfamily E member 1)
Diseases named in the same sentence as CYP2E1 in open-access papers (continued):
Sharing a sentence is not in itself a finding about the gene and the disease.
tumor (continued). "In the present study, we compared the pattern expression of CYP1A1, CYP1A2, CYP1B1, CYP2E1, CYP2W1, CYP3A4 and CYP3A5 in paired tumor and normal tissue of child patients with RMS." (PMID 24699256, 2014). "When comparing the relative mRNA concentration of CYP1B1, CYP2E1, CYP3A4, and CYP3A5 we detected in general higher regulation in tumor than their corresponding normal adjacent samples." (PMID 24699256, 2014). "In addition, pericentral hepatic markers and WNT target genes, such as CYP2E1 and GLUL, were broadly expressed in the tumor region, contrasting with the zonated pattern in the normal tissue." (PMID 39567475, 2024). "Male wild-type mice exposed postnatally to a tumor-causing dosage of ABP also experienced oxidative stress, but neither male Cyp2e1(/) mice nor female mice did." (PMID 37371985, 2023). "In conclusion, we discovered a previously unknown pro‐tumorous mechanism in which the CYP2E1‐PPAR‐γ‐STAT‐1/NF‐κB/STAT‐3/STAT‐6 axis induced GBM cell proliferation and inhibited apoptosis to fuel tumorigenesis and tumor growth." (PMID 37283464, 2023). "Further analysis indicated positive correlation between CYP2E1 activity and tumor severity in GBM rats, evidenced by significantly inverse correlation for AUC0‐∞ and positive correlation for CL with tumor weight." (PMID 37283464, 2023). "P1, which constituted a major fraction of HB tumor cells and had the highest C1 group score, exhibited a more mature hepatocyte-like phenotype, expressing the highest level of ALB as well as liver metabolism genes (e.g., CYP2E1, GSTA1, G6PC)." (PMID 35860547, 2022). "On a genetic level, a comparable study in a set of 20 paired samples of tumour and adjacent normal breast tissues from patients with infiltrating ductal carcinoma identified the expression of CYP1B1, CYP2B6, CYP2C, CYP2D6, CYP2E1, CYP4B1 and CYP11A1 in both tumour and control tissues." (PMID 33809117, 2021). "Furthermore, the gene expression alterations in tumour tissues were consistent with the in vitro observations: upregulation of PTGS2 and CYP2E1 and down-regulation of TP63 and KRT5." (PMID 33359448, 2021). "CYP2E1 expression in normal and tumor tissues did not correlate with any of the examined characteristics (P>0.05)." (PMID 24699256, 2014). "Expression of CYP2E1 mRNA was found to be significantly higher in tumor tissue, however no relation was found with protein levels." (PMID 24699256, 2014). "Thus, the aim of the present study was to determine the mRNA expression pattern of seven representative CYPs (e.g., CYP1A1, CYP1A2, CYP1B1, CYP2E1, CYP2W1, CYP3A4, and CYP3A5) in paired tumor and normal tissue of childhood patients with RMS." (PMID 24699256, 2014). "Compounds that inhibit or suppress CYP2E1 activity affect AOM metabolism and hence may prevent hypermethylation and carcinogenesis of intestinal cells, and thereby early neoplastic ACF formation as well as other neoplasms." (PMID 31540047, 2019). "However to CYP2E1 no relation was found between mRNA and protein, since CYP2E1 protein was only detected in one tumor sample." (PMID 24699256, 2014). "As with styrene, the higher conversion of ethylbenzene to CYP2E1 metabolites in mouse lung are likely responsible for changes observed in mouse lung at exposures below 200 ppm, but these do not appear to correspond with neoplasia or tumors at higher concentrations." (PMID 38059960, 2024). "We finally obtained a list of only five genes (AGXT; ALDOB; CYP2E1; IGFBP3; TOP2A) that were differentially expressed in tumor and nontumor tissues across studies, and were significantly correlated to HCC prognosis." (PMID 31771612, 2019). "Using real time quantitative RT-PCR, the gene expression pattern of CYP1A1, CYP1A2, CYP1B1, CYP2E1, CYP2W1, CYP3A4, and CYP3A5 were analyzed in tumor and adjacent non-tumor tissues from 13 child RMS patients." (PMID 24699256, 2014).
metabolic disorders (7 papers, 2020 to 2025). "In addition, the increased risk of malignancy and metabolic diseases has been associated with elevated CYP2E1 expression, as was found in this study." (PMID 35739948, 2022). "Furthermore, we found that pharmacological inhibition of CYP2E1 or ADH by 4-MP suppressed the maternal metabolic disorders caused by ethanol exposure before pregnancy and subsequently rescued fetal development and growth." (PMID 32572070, 2020). "Correlatively, our data provide several lines of evidence showing that pharmacological inhibition of CYP2E1 by 4-MP had therapeutic effects on abnormal fetal development and maternal metabolic disorders in ethanol-fed mice." (PMID 32572070, 2020). "The CYP4A and CYP2E1 genes are activated in fasting and several metabolic disorders, suggesting a synergistic role in preventing fatty acid-induced lipotoxicity with the consequence of increased liver cholesterol and lipogenesis leading to increased Lipid Droplet (LD) deposition." (PMID 40452921, 2024).
infection (6 papers, 2011 to 2025). The state of being infected such as from the introduction of a foreign agent such as serum, vaccine, antigenic substance or organism. "Transcript levels of some of the key DMEs were upregulated in the liver of the infected mice, 8 weeks post-infection like Nat2, Cyp2e1, Slco1b2, Ces1, Ces2, and Aadac (upregulated by almost 2–3-fold)." (PMID 41358489, 2025). "Several of these genes are important in regulating oxidative stress to infection including Cyp2e1, aldehyde dehydrogenase (Aldh1a7) and sulphotransferase 1e1 (Sult1e1)." (PMID 21338512, 2011). "In addition, for other cell organelles, peroxisome-related genes (Adipor1, Adipor2, Ppara), Cytochrome P450-related genes (Cyp2e1) and Cytochrome c-related genes (Cycs) were significantly lower in the inf + nisin group than the infection group." (PMID 38233485, 2024). "The adoption of an hepatocyte-like phenotype by B-13 cells in response to AdV-SGK1F infection was confirmed by detection of liver-enriched and liver-specific gene transcripts Cyp2e1 and CpsI respectively, similarly to cells treated with dexamethasone for 14 days." (PMID 31242206, 2019).
hematological disorders (2 papers, 2018). "Carrier individuals of the variant allele of CYP2E1 -1293G>C/-1053C>T (rs3813867/rs2031920) who are also exposed to polycyclic aromatic derivatives may have a high CYP2E1 activity and are prone to develop hematological malignancies, such as AML and ALL." (PMID 30154939, 2018). "In addition, hematological disorders may also be related to polymorphisms in genes encoding xenobiotic-metabolizing enzymes, such as cytochrome P4502E1 (CYP2E1), myeloperoxidase (MPO), NAD(P)H:quinone oxidoreductase 1 (NQO1), and glutathione S-transferase (GST)." (PMID 30154939, 2018).
liver (2 papers, 2019 to 2024). "Ethanol taken induces CYP2E1 expression, which is an active producer of reactive oxygen species (ROS) and a promoter of alcohol‐induced oxidative liver injury." (PMID 39055233, 2024).
neurodegenerative disease (2 papers, 2023 to 2025). A disorder of the central nervous system characterized by gradual and progressive loss of neural tissue and neurologic function. "Genetic variation in CYP2E1, which has been documented in the Chinese population, is an established cause of significant inter-individual differences in drug response and the risk of neurodegenerative disease." (PMID 37441677, 2023). "A key distinction between alcohol-mediated brain damage and other neurodegenerative diseases could be the selective activation of CYP2E1 by alcohol, since CYP2E1 is not induced by aging-related neurodegeneration." (PMID 40227291, 2025).
brain disorder (1 paper, 2017). A disease affecting the brain or part of the brain. "The genetic variant or epigenetic changes to CYP2E1 make it more susceptible to an efficient metabolism but, conversely, more vulnerable to bioactive compounds formed through CYP2E1 activity and has been related to different brain disorders." (PMID 28163821, 2017). "Alterations in these functions of CYP2E1 are related to different brain disorders." (PMID 28163821, 2017). "Finally, we describe the relation of CYP2E1 in brain disorders, including the behavioral relations for alcohol consumption via CYP2E1 metabolism." (PMID 28163821, 2017).
mental illness (1 paper, 2022). "Additionally, there are potential genetic effects influencing the methylation level of CYP2E1, hence, information about family history of mental illness, and ideally, the methylation levels of other family members should also be measured in future studies." (PMID 36494682, 2022).
CYP2E1 also shares sentences with these, for which no sentence is quoted: primary biliary cholangitis (3 papers); Alzheimer disease (2); autism (2); emphysema (2); esophageal squamous cell carcinoma (2); gout (2); hepatitis B (2); inflammation (2); influenza (2); nephropathies (2); neurological disease (2); pharyngeal cancer (2); squamous cell carcinoma (2); ulcerative colitis (2); Acute hepatitis (1); allergic rhinitis (1); amyloidosis (1); atherosclerosis (1); atrial fibrillation (1); autoimmune hepatitis (1); benign tumors (1); cardiac hypertrophy (1); Cerebral ischemia (1); cholestasis (1); Choreoathetosis (1); chronic hepatitis B (1); chronic kidney disease (1); co-infection (1); Cognitive impairment (1); coronary artery disease (1).
A further 44 diseases each share a sentence with CYP2E1 in 1 paper.